GPR137 (G protein-coupled receptor 137)
Description:
Lysosomal integral membrane protein that may regulate MTORC1 complex translocation to lysosomes. May play a role in autophagy. May activate Wnt/beta-catenin signaling to modulate epithelial cell function.
Synonyms: C11orf4; GPR137A; TM7SF1L1
Tractability: Antibody: UniProt predicts a signal peptide or a membrane-spanning region.
Gene: Protein-coding gene on chromosome 11 (64,270,062 to 64,289,494, forward strand). Ensembl gene ENSG00000173264.
Subcellular location: Lysosome membrane
Subcellular location (Human Protein Atlas): Nucleoli; Nucleoplasm; Actin filaments
Gene Ontology:
Biological process: negative regulation of bone resorption; negative regulation of osteoclast differentiation; positive regulation of TORC1 signaling; regulation of autophagy
Cellular component: lysosomal membrane
Genetic constraint (gnomAD): Loss-of-function variants: 20 observed, 38.44 expected, observed/expected ratio (o/e) 0.52, 90% interval 0.37 to 0.76. The upper end of that interval is the gene's LOEUF score, 0.76, which puts it in group 3 of 6, group 1 being the genes least tolerant of losing a copy. Missense variants: 456 observed, 527.89 expected, observed/expected ratio (o/e) 0.86, 90% interval 0.8 to 0.93. Synonymous variants: 226 observed, 234.02 expected, observed/expected ratio (o/e) 0.97, 90% interval 0.87 to 1.08.
Homologues: Orthologues: pig GPR137 (97% identical), guinea pig GPR137 (96% identical), mouse Gpr137 (95% identical), dog GPR137 (95% identical), chimpanzee GPR137 (89% identical), macaque GPR137 (88% identical), rat Gpr137 (86% identical), zebrafish gpr137 (47% identical). Paralogues in human: GPR137B (48% identical), GPR137C (39% identical).
Diseases named in the same sentence as GPR137 in open-access papers:
GPR137 is named in the same sentence as 17 diseases in open-access papers, as found by Europe PMC text mining. Sharing a sentence is not in itself a finding about the gene and the disease. The quoted sentences say what the papers report.
ovarian carcinoma (5 papers, 2023 to 2025). A malignant neoplasm originating from the surface ovarian epithelium. "For example, gpr137 plays pro-oncogenic roles in ovarian cancer through regulating the PI3K/AKT pathway." (PMID 40356894, 2025). "Examination of the cDNA expression profile disclosed elevated GPR137 expression in the neoplastic tissues of ovarian cancer patients." (PMID 38021163, 2023). "The findings of the study indicate that ovarian cancer patients with elevated expression of GPR137, NDEL1, and TUBA1A genes experienced a statistically significant increase in survival time, as demonstrated by Kaplan-Meier survival analysis." (PMID 38021163, 2023). "Bioinformatics prediction unveiled a close association of GPR137, NDEL1, DYNC1H1, and TUBA1A with ovarian cancer development and prognosis." (PMID 38021163, 2023). "Further, multiple gene correlation analyses revealed a significant positive linear relationship between GPR137 expression in ovarian cancer tissues and the expression levels of NDEL1, DYNC1H1, and TUBA1A." (PMID 38021163, 2023). "Recently, it has been reported that GPR137 also plays a crucial role in tumor progression and metastasis, including ovarian cancer (OC), and GPR137 is found to be highly expressed in clinical OC tissues, providing with possible prognostic value of GPR137 in OC." (PMID 39856733, 2025). "Analysis of pathological stage indicated differential expression levels of GPR137 and DYNC1H1 across varying stages of ovarian cancer." (PMID 38021163, 2023). "Moreover, by examining clinical data, we found that the expression of four genes, GPR137, NDEL1, DYNC1H1, and TUBA1A, differed significantly between tumor tissues and normal tissues, and their expression levels were significantly associated with poor prognosis of ovarian cancer patients." (PMID 38021163, 2023). "Knockdown of GPR137 downregulated the ERK and AKT pathways in osteosarcoma and ovarian cancer cells, respectively." (PMID 36436172, 2023). "In the present study, we have revealed that GPR137 is upregulated in ovarian carcinomas compared to normal non-cancerous ovarian tissues, which is consistent with the GEPIA data and with a previous study." (PMID 39856733, 2025). "Thus, the findings of the analysis indicate a significant correlation of the expression levels of GPR137, NDEL1, DYNC1H1, and TUBA1A with the advancement and prognosis of ovarian cancer." (PMID 38021163, 2023).
prostate carcinoma (4 papers, 2017 to 2025). A carcinoma that arises from epithelial cells of the prostate gland. "Previous studies have identified that GPR137 is involved in the proliferation of tumor cells in several cancers, including ovarian, pancreatic, hepatoma, bladder, and prostate cancers, as well as medulloblastoma." (PMID 38163861, 2024). "GPR137 suppression also decreases the migration and invasive abilities of PC-3 cells, suggesting that GPR137 plays a role in prostate cancer progression and metastasis." (PMID 31835700, 2019). "On the other hand, GPR137 expression has been shown to be upregulated in prostate cancer tissues compared with paracancerous tissues." (PMID 31835700, 2019). "As a member of GPR, GPR137 has been shown to contribute to malignant phenotypes of multiple cancers, such as gastric cancer, pancreatic cancer, bladder cancer, and prostate cancer." (PMID 39856733, 2025). "Moreover, knockdown of GPR137 resulted in decreased cell proliferation and colony formation in PC-3 and DU145 prostate cancer cell lines, and was associated with cell cycle arrest at G0/G1 phase." (PMID 31835700, 2019). "Indeed, silencing of GPR137 resulted in a downregulation of SNAI1/SNAIL and SNAI2/SLUG and a corresponding increase in E-cadherin expression in human prostate cancer cells." (PMID 28975893, 2017).
bladder cancer (3 papers, 2018 to 2025). "Patients with high GPR137 expression exhibited shorter overall survival time than those with low expression in bladder cancer 30,31." (PMID 38287071, 2024). "GPR137 has been reported to be involved with the proliferation of tumor cells in several cancers, including gastric, colon, pancreatic, hepatoma, urinary bladder cancer, medulloblastoma and malignant glioma." (PMID 29422775, 2018).
gastric cancer (3 papers, 2015 to 2025). A primary or metastatic malignant neoplasm involving the stomach. "Consistently, the protein expression of GPR137 was obviously higher in human gastric cancer AGS cells and SGC-7901 cells than that in human normal gastric epithelial GES-1 cells." (PMID 38163861, 2024). "Overall, by human gastric cancer cell model, xenograft model and clinical tissue samples, the present study suggests that the GPR137-Hippo signaling plays a key role in regulating GC cell malignancy." (PMID 38163861, 2024). "The present study therefore aimed to investigate the role of GPR137 in gastric cancer cell growth using RNA interference (RNAi)." (PMID 25514843, 2015). "The expression of GPR137 was therefore successfully inhibited by infection with Lv-shGPR137 in gastric cancer cells." (PMID 25514843, 2015). "In order to investigate the role of GRP137 in gastric cancer, the expression levels of GPR137 were assessed in a subset of gastric cancer cell lines, including MKN28, SGC-7901, MGC80-3 and AGS." (PMID 25514843, 2015). "The results of the present study demonstrated that GPR137 was able to mediate gastric cancer cell growth in vitro." (PMID 25514843, 2015). "In conclusion, to the best of our knowledge, the present study was the first to define GPR137 as a functional mediator of gastric cancer cell growth." (PMID 25514843, 2015). "The observed attenuation of colony formation indicated that GPR137 knockdown impaired the anchorage-independent growth of gastric cancer cells." (PMID 25514843, 2015). "Overexpression of GPR137 potentiates human gastric cancer AGS cell malignancy, including proliferation, migration, invasion, colony formation and xenograft growth in nude mice in vivo, whereas knockout of GPR137 by CRISPR/Cas9 gene editing exerts the opposite effects." (PMID 38163861, 2024). "It was therefore suggested that specific ligands existing in the stomach and brain may be involved in GPR137-mediated gastric cancer cell growth." (PMID 25514843, 2015). "GPR137 is highly expressed in multiple human gastric cancer cell lines." (PMID 25514843, 2015). "GPR137 may therefore contribute to gastric cancer cell growth via manipulation of G2/M phase regulators." (PMID 25514843, 2015). "Elucidating the role of GPR137 in gastric cancer cell growth is of biological significance." (PMID 25514843, 2015). "The present study identified a novel function of GPR137 to gastric tumorigenesis, and may provide a target for the development of gastric cancer therapeutics." (PMID 25514843, 2015). "Knockdown of GPR137 significantly inhibited gastric cancer cell growth in vitro." (PMID 25514843, 2015). "A GPR137 short hairpin RNA (shRNA)-expressing vector was transfected into AGS and MGC80-3 gastric cancer cells, and the subsequent depletion of GPR137 resulted in a significant reduction in cell proliferation and colony formation, as determined by MTT and colony formation assays." (PMID 25514843, 2015). "Therefore, it was hypothesized that GPR137 may regulate the cell cycle by influencing G2/M phase molecules, which mediate microtubule and/or spindle activities, and in this way promote gastric cancer cell growth." (PMID 25514843, 2015). "To further investigate the role of GPR137 in regulating the Hippo pathway in GC, we used CRISPR/Cas9 genome editing technology to knockout GPR137 in AGS gastric cancer cells." (PMID 38163861, 2024). "However, GPR137 potentially regulates gastric cancer cell growth via alternative mechanisms, rather than lysosome signaling pathways." (PMID 25514843, 2015).
leukemia (2 papers, 2018 to 2024). A malignant (clonal) hematologic disorder, involving hematopoietic stem cells and characterized by the presence of primitive or atypical myeloid or lymphoid cells in the bone marrow and the blood. "Using siRNA technology, GPR137 was demonstrated to be associated with the proliferation of leukemia cells." (PMID 29422775, 2018). "The decreased proliferation was associated with silenced GPR137-induced cell cycle arrest, which causes leukemia cells arrest in G0/G1 phase of cell cycle." (PMID 29422775, 2018). "The expression of GPR137 is associated with the proliferation of leukemia cell lines." (PMID 29422775, 2018). "In this study, lentivirus-mediated RNA interference (RNAi) was employed to investigate the role of GPR137 in two leukemia cell lines K562 and HL60." (PMID 29422775, 2018). "It is shown in this study that there was high level of constitutive expression of GPR137 in leukemia cells." (PMID 29422775, 2018). "In this study, the effect of under-expression of GPR137 on inhibiting the proliferation of leukemia cells is explored, to identify a novel target for leukemia treatment." (PMID 29422775, 2018). "It was shown that both Cylin D1 and CDK4 were reduced in leukemia cells when GPR137 expression was silenced." (PMID 29422775, 2018). "G protein-coupled receptor 137 (GPR137) has been recognized as a key player in carcinogenesis and cancer progression, and its down regulation has been shown to inhibit proliferation and promote apoptosis in leukemia cells." (PMID 38287071, 2024). "Down regulation of GPR137 could inhibit proliferation and promote apoptosis in leukemia cells, which makes it a promising bio-marker and therapeutic target to treat patients with leukemia." (PMID 29422775, 2018). "In this study, the influence of GPR137 on the proliferation of leukemia were investigated, and whether it can be used as a therapeutic target were also explored." (PMID 29422775, 2018). "In addition, down regulation of GPR137 arrested cells in the G0/G1 phase of cell cycle and induced apoptosis in both leukemia cell lines K562 and HL60." (PMID 29422775, 2018). "GPR137 has been shown to play an important role in several different kinds of cancers, but its role in leukemia is currently unknown." (PMID 29422775, 2018). "However, the functions of GPR137 in leukemia were previously unknown." (PMID 29422775, 2018).
colon cancer (1 paper, 2017). "Little is known about GPR137, an orphan GPCR whose knockdown leads to reduced proliferation of several cancer cell lines, including colon cancer cells." (PMID 28975893, 2017).
cancer (12 papers, 2015 to 2025). A tumor composed of atypical neoplastic, often pleomorphic cells that invade other tissues. "Moreover, GPR137 regulates autophagy, cell growth, and cell proliferation and is implicated in various cancers." (PMID 41416692, 2025). "Furthermore, low levels of ESRP1 and increased levels of the long version of GPR137 were associated with poorer outcomes for cancer patients." (PMID 28975893, 2017). "GPR137 is an orphan receptor widely expressed in human tissues and has been previously studied for its role in cancer cell growth and proliferation." (PMID 36766718, 2023). "Study shows the over-expression of GPR137 is associated with the growth of tumor cells, while under-expression of GPR137 has been shown to inhibit cell proliferation in several different types of cancers, but its role in amino acid sensing is still unclear." (PMID 37164974, 2023). "GPR137 is highly expressed in several cancer types and is directly involved in cancer cell proliferation and metastasis." (PMID 36766718, 2023). "The role of GPR137 in human cancers is poorly understood, and the function of GPR137 and its regulatory mechanism in human cancer has remained to be elucidated." (PMID 25514843, 2015). "The orphan receptor GPR137 is an integral membrane protein involved in several types of cancer." (PMID 40356894, 2025). "In this work, we have elucidated that GPR137 inhibits Hippo signaling by suppressing MST kinase phosphorylation and its binding to LATS in GC cells, providing with the evidence that MST kinase activity is closely associated with cancers." (PMID 38163861, 2024). "These opposing effects of GPR137 might be due to differences in GPR137-mediated signals between cancer and neuronal cells." (PMID 36436172, 2023). "Whether GPR137 functions as a key mediator of cancer growth in the same way as other GPRs do has remained elusive." (PMID 25514843, 2015). "Mechanistically, GPR137 enhances stabilization of RAB8A mRNA and the up-regulated RAB8A expression activates HH signaling by destroying the SuFu-GLI1 complex, leading to the release of GLI1 and thereby its translocation into the nucleus to trans-activates cancer-associated target genes." (PMID 39856733, 2025). "Similarly, GPR137 could have a role in hyperproliferative diseases since it can regulate cell growth by interacting with Rag-mTORC1 signaling and induce proliferation in cancer cells." (PMID 37398171, 2023). "The orphan receptor, G protein-coupled receptor 137 (GPR137), is an integral membrane protein involved in several types of cancer." (PMID 36436172, 2023). "Other GDTLs we detected like CXCR1, VASP, ZYX, GPR137 and GOLPH3 were reported as known markers in many cancers." (PMID 33179221, 2021).
tumor (12 papers, 2015 to 2025). "Over-expression of G protein-coupled receptors 137 (GPR137) are associated with the growth of tumor cells, but under-expression of GPR137 has shown to inhibit cell proliferation in several different types of cancers." (PMID 29422775, 2018). "A further potential mechanism underlying the tumor-promoting effect of GPR137 is that GPR137 may regulate molecules which are involved in cell cycle regulation." (PMID 25514843, 2015). "To investigate the role of GPR137 in OC, we first determined its clinical implication by comparing the expression of GPR137 in 10 pairs of OC tissues and adjacent non-tumor tissues." (PMID 39856733, 2025). "In this study, we have confirmed that the orphan receptor, GPR137, acts as a tumor promoter bolstering OC cell propagation through the RAB8A-mediated HH signaling activation." (PMID 39856733, 2025). "To first examine the expression of GPR137 in tumor tissue from GC patients, we utilized the database online." (PMID 38163861, 2024). "Such is the case for GPR101 in macrophages which affects host immune response; meanwhile, GPR137 can inhibit cellular proliferation and promote neuronal differentiation in tumor cells." (PMID 39767576, 2024). "Our study also revealed that the differential expression of GPR137 expression and EPB41L1 is associated with tumours of Gleason scores 3 + 4 = 7 and 8, respectively." (PMID 31835700, 2019). "Taken together, these results demonstrate that GPR137 plays a tumor-stimulative role in OC." (PMID 39856733, 2025). "Consistently, compared with the control AGS cells, the GPR-137-expressing lentiviruses-infected AGS cells resulted in the xenografts with the significantly increased tumor weight and tumor volume in nude mice, suggesting that GPR137 regulates AGS cell malignancy both in vitro and in vivo." (PMID 38163861, 2024). "RNA interference (RNAi)-mediated downregulation of GPR137 inhibits tumor cell growth." (PMID 36436172, 2023). "Previous studies reported that GPR137 plays a role in tumor cell proliferation." (PMID 36436172, 2023). "In addition to tumor cells, GPR137 is expressed ubiquitously, including in the central nervous system (CNS)." (PMID 36436172, 2023). "Furthermore, the ratio of specific GPR137 isoforms varied in tumor versus normal intestinal human samples, and expression of a specific ESRP1-dependent GPR137 isoform predicted CRC patient survival." (PMID 28975893, 2017). "Moreover, the ratio of specific GPR137 isoforms is different in tumor versus normal intestinal tissue, and expression of a specific ESRP1-dependent GPR137 isoform predicts CRC patient survival." (PMID 28975893, 2017). "The results of the present study demonstrated the tumor promoting-effect of GPR137 in the stomach." (PMID 25514843, 2015).
infection (2 papers, 2015 to 2025). The state of being infected such as from the introduction of a foreign agent such as serum, vaccine, antigenic substance or organism. "To finally test the oncogenic role of GPR137-RAB8A signal axis in OC progression in vivo, we established a SK-OV-3 cell line and an A2780 cell line that stably expressed GPR137-shRNA and RAB8A-shRNA by infection of levtiviruses carrying the shRNA sequences targeting GPR137 or RAB8A, respectively." (PMID 39856733, 2025). "Furthermore, compared with the control vector Lv-shCon, the positive infection rate and the GPR137 mRNA expression levels in Lv-shGPR137-infected AGS cells were significantly decreased (P<0.01)." (PMID 25514843, 2015). "Concomitantly, the protein expression levels of GPR137 were markedly reduced in AGS and MGC80-3 cells following infection with Lv-shGPR137." (PMID 25514843, 2015).
adenocarcinoma of the (1 paper, 2017). "The GPR137 gene has also been identified in two fusions: with PAFAH1B2 and USP32 in adenocarcinoma of the lung and of the breast, respectively." (PMID 28186972, 2017).
GPR137 also shares sentences with these, for which no sentence is quoted: hepatoma (2 papers); medulloblastoma (2); osteosarcoma (2); pancreatic cancer (2); colitis (1); malignant glioma (1); ovarian tumor (1).